CALR (calreticulin)
Diseases named in the same sentence as CALR in open-access papers (continued):
Sharing a sentence is not in itself a finding about the gene and the disease.
tumor (continued). "Next, the protein levels of GRP78, GRP94 and Calreticulin were determined in tumour and matched normal tissues from the same cohort of CRC patients." (PMID 29374142, 2018). "Anthracyclines, in particular, induce tumour cell damage and release/expose calreticulin and other endoplasmic proteins." (PMID 29390966, 2018). "These agents promote the release of tumor antigens in conjunction with the release of signals that activate APCs, including ATP, high mobility group box-1 (HMGB1) and interferon-β (IFNβ), and the exposure of calreticulin on the surface of tumor cells." (PMID 30208166, 2018). "Several studies have showed that the translocation of calreticulin to the plasma membrane induced by radiation is critical for the recognition of dying tumour cells by dendritic cells." (PMID 29702669, 2018). "Second, C/EBP-β LIP down-regulated Pgp and up-regulated calreticulin that triggered the dendritic cell (DC)-mediated phagocytosis of tumor cell, followed by the activation of anti-tumor CD8+T-lymphocytes upon doxorubicin treatment." (PMID 30482226, 2018). "ER resident chaperones including calreticulin lowered cell death and have been associated with ERS induction in tumor cells." (PMID 30326660, 2018). "Although more than thirty CALR mutations have been identified, all result in the generation of a common, 36-amino acid novel C-terminal CALR peptide, representing a tumor-specific neo-antigen." (PMID 30400835, 2018). "Another means to enhance the anti-tumor immune response would be to combine JAK2/CALR-vaccines with PD-1 specific mAbs, as treatment with these drugs have been shown to enhance the amount of neo-antigen specific T cells in peripheral blood." (PMID 30327655, 2018). "For instance HMGB1, calreticulin, and viral/cellular DNA can be released in the tumor microenvironment and elicit immune-cell recruitment." (PMID 30514385, 2018). "Increased phagocytosis of tumor cells mediated by targeting CD47 was inhibited by CALR blockade and its interaction with low density lipoprotein receptor-related protein-1 (LRP1)." (PMID 28815041, 2017). "Tumor re-sensitization to anti-estrogen therapy mediated by GRP78 targeting was correlated with increased levels of calreticulin (CALR) and high molecular group box 1 (HMGB1) protein, known pro-immunologic cell death and phagocytic signals." (PMID 28815041, 2017). "Expression of immunogenic death markers on the cell surface of R2016 treated tumor cells including calreticulin (CRT) and heat shock proteins (HSPs) was increased along with the induction of their genes." (PMID 28282460, 2017). "CALR also functions as an “eat me” signal and induces the immunogenic tumor cell death after translocation from the ER to the cytosol and the cell surface." (PMID 29228584, 2017). "The correlation between CALR expression levels and tumorigenesis has been extensively studied in various cancers and most related reports have indicated that tumor tissues express significant higher levels of CALR than normal tissues do." (PMID 28423550, 2017). "As immunogenic cell death signal, tumor cell surface expression of calreticulin (CRT) and heat shock proteins (HSP60, HSP70, and HSP90) were measured after R2016 treatment." (PMID 28282460, 2017). "We used flow cytometry to measure the percentage of tumor cells expressing cell surface calreticulin (ecto-CRT) after treatment with NPS at a range of energies or with two different anthracyclines (doxorubicin and mitoxantrone) at two different concentrations." (PMID 28428881, 2017). "One key feature of the tumor cell ICD is the appearance of surface-exposed calreticulin (CRT) on the cell membrane." (PMID 27248319, 2016). "Here, we show that while 223Ra increases expression of MHC-I, it can also induce ER stress in tumor cells and subsequently lead to upregulation and surface translocation of calreticulin." (PMID 27893426, 2016).
tumor (continued). "Anthracyclines, in particular, induce tumour cell damage and exposure of calreticulin and other endoplasmic reticulum proteins, secretion of ATP, and release of the high-mobility group box 1 (HMGB1) molecules." (PMID 27777963, 2016). "Our data demonstrate that miR-27a acts as an oncomiRNA, represses MHC class I expression through calreticulin downregulation and affects tumour progression." (PMID 26913609, 2016). "In previous studies, inhibiting this interaction through the use of a calreticulin blocking peptide significantly reduced the sensitivity of irradiated tumor cells to CTL-mediated lysis." (PMID 27893426, 2016). "Two-dimensional gel protein electrophoresis and MALDI-TOF analysis showed upregulation of calreticulin expression in tumor tissues as compared to the normal adjacent tissues." (PMID 27418879, 2016). "The presence of calreticulin blocking peptide during the CTL killing assay completely abrogated any increase in tumor-cell lysis that occurred following radiation treatment." (PMID 27893426, 2016). "IL-12 is mainly produced by DCs in response to tumor-associated antigens or during the release of damage-associated molecular patterns (DAMPs) such as HMGB1, HSP, and calreticulin in the tumor microenvironment." (PMID 26745884, 2016). "Other released DAMPs resulted from tumor necrosis, such as ATP, calreticulin, and HMGB1 would be worthy further investigating." (PMID 27256519, 2016). "Surface calreticulin has the ability to bind CTLs and enhance tumor-cell lysis, possibly due to more stable and/or prolonged tumor cell/T cell interaction." (PMID 27893426, 2016). "RT has been shown to enhance APC activity by inducing the translocation of calreticulin (CRT) to the plasma membrane of the dying tumor cell." (PMID 27416962, 2016). "Synergy between oxaliplatin and pyrolipid-induced PDT kills tumour cells and provokes an immune response, resulting in calreticulin exposure on the cell surface, antitumour vaccination and an abscopal effect." (PMID 27530650, 2016). "One of the functional consequences of ER stress induction in tumor cells is translocation of calreticulin to the cell surface, where it enhances target killing by enhancing tumor-cell/T-cell recognition." (PMID 27893426, 2016). "Enhanced tumor-cell lysis was facilitated by calreticulin surface translocation following 223Ra exposure." (PMID 27893426, 2016). "It is likely that ER stress is the main driver of calreticulin translocation and is thus responsible for increased tumor sensitivity to CTL lysis." (PMID 27893426, 2016). "Immunofluorescence analysis revealed that the increase in CTL killing was accompanied by augmented protein expression of MHC-I and calreticulin in each tumor type, molecules that are essential for efficient antigen presentation." (PMID 27893426, 2016). "The facts that tumor cells decorated with calreticulin are more efficiently phagocytosed by dendritic cells and have increased immunogenicity are more consistent with the role of calreticulin as promoter of their death and disposal." (PMID 25692097, 2015). "In non-Hodgkin's lymphoma patients receiving autologous DCs loaded with tumor cell antigens (generated by heat shock or irradiation), levels of CALR exposure on cancer cells provided an independent prognostic marker." (PMID 26486085, 2015). "During cellular apoptosis, calreticulin (CRT) which is a Ca2+-binding protein in the endoplasmic reticulum would translocate to the tumor cell surface to act as a crucial determinant for phagocytosis by DCs and macrophages." (PMID 26343191, 2015). "We compared CALR levels between tumour tissue and corresponding normal tissue (of the same tissue-type), in order to obtain Oncomine profiles/analyses with significant CALR over/under-expression ratios for each combination, which are shown in respective boxes." (PMID 26314964, 2015). "Our data indicate that CALR have upregulated GLUT-1 expression compared with CALS tumours, consistent with an increased Warburg effect." (PMID 25742484, 2015).
tumor (continued). "Injection of calreticulin-exposing dying tumor cells prevented tumor growth upon re-challenge with viable tumor cells." (PMID 25688334, 2015). "The exposed CALR (ecto-CALR) was found to be critical for ICD as knockdown of CALR expression significantly hampered anti-tumor immunity." (PMID 26486085, 2015). "Selective knock-down of calreticulin reduced the phagocytic uptake of anthracyclin treated cells by dendritic cells and abolished T-cell-mediated elimination of the tumor." (PMID 25688334, 2015). "NTP levels were not reproducibly detectable in the 31P NMR spectra of tumour extracts, but the consistent and significant increase in CALR PCr levels suggests that the drug-resistant tumours have improved bioenergetics." (PMID 25742484, 2015). "ERp57 and calreticulin extracellular expression levels correlated and also co-translocated to the surface of mitoxantrone treated tumor cells." (PMID 25688334, 2015). "31P NMR analysis of CALS and CALR tumour extracts corroborated the elevation in GPC and PCr levels and additionally revealed a rise in glycerophosphoethanolamine (GPE) and a fall in phosphoethanolamine (PE) levels in CALR relative to CALS tumours." (PMID 25742484, 2015). "Of note, the overexpression of chaperones has been considered as a sign of increased malignancy, with calreticulin in particular being over-expressed in numerous tumor tissues possibly to cope with increased ER stress." (PMID 25688334, 2015). "In this role, calreticulin becomes exposed on the surface of tumor cells treated by several types of cancer therapy including photodynamic therapy (PDT)." (PMID 25692097, 2015). "In this respect, it is interesting to mention that the only study in which clinical responses to tumor expressed calreticulin was found, has been described in NHL patients." (PMID 25688334, 2015). "In summary, the present study demonstrates that externally added calreticulin protein, which has the ability to bind to tumor cells sustaining injury/stress from PDT treatment, can serve as an effective adjuvant augmenting tumor control with this therapy." (PMID 25692097, 2015). "Here, calreticulin is translocated to the cell membrane during early (pre-apoptotic) stages of dying tumor cells, which facilitates efficient uptake by dendritic cells." (PMID 25688334, 2015). "Again, surface calreticulin induced maturation of human immature dendritic cells, and elicited an anti-tumor immune response in mice." (PMID 25688334, 2015). "The results with immunocompetent mice showed that the adjuvant calreticulin treatment rendered a significant improvement in tumor response to PDT from marginally curative to the solid levels of about 40% cure rates." (PMID 25692097, 2015). "Briefly, anthracycline or radiation therapy trigger the translocation of calreticulin to the pre-apoptotic tumor cell surface, which is dependent on the induction of an ER-stress response." (PMID 25750898, 2015). "Several authors have suggested that this overriding “eat me” signal on tumor cells is calreticulin, which cannot be substituted by other chaperones." (PMID 25688334, 2015). "Next we evaluated the predictive value of CALR expression when the patients are categorized into different cohorts according to the different tumour stages." (PMID 26314964, 2015). "In PDT-vaccine protocol, where PDT-treated SCCVII cells are used for vaccination of SCCVII tumor-bearing mice, adding recombinant calreticulin to cells before their injection produced improved therapeutic effect." (PMID 25692097, 2015). "γ-Synuclein overexpression is known to cause an increase in proliferation, invasiveness and metastasis, and γ-synuclein, along with calreticulin and catechol-o-methyltransferase, is reported to be a tumor marker in BCa." (PMID 25915536, 2015). "Such surface-exposed calreticulin induces the uptake of dying cancer cells by CD11c-positive myeloid dendritic cells, leading to tumor antigen presentation to T-cells and concomitant clonal T-cell expansion." (PMID 25688334, 2015).
tumor (continued). "This calreticulin translocation is important for the immunogenicity of dying tumor cells, which is key to the success of chemotherapy." (PMID 25230046, 2014). "Knockdown of PERK abrogated the translocation of calreticulin to the cell surface and significantly reduced irradiated tumor cells' sensitivity to CTL lysis." (PMID 24480782, 2014). "Our study also established the biomedical linkage of the critical over-expression of CALR, annexin A2 and annexin A3 between the urine and tumor tissues of UTUC patients." (PMID 24884814, 2014). "Another important function of calreticulin at the cell surface is to mediate phagocytosis of apoptotic or dying tumor cells." (PMID 25230046, 2014). "Specifically, cabozantinib treatment upregulated the expression of MHC-I molecules, ICAM-1, Fas, and calreticulin on tumor cells." (PMID 25388653, 2014). "As expected, abrogation of cell-surface expression and decrease in total protein levels following siRNA knockdown of calreticulin significantly inhibited CTL lysis of tumor cells exposed to sublethal radiation." (PMID 24480782, 2014). "Vasostatin, the 180 amino acid N-terminal fragment of the calreticulin protein, is reported to be a potent endogenous inhibitor of angiogenesis, suppressing tumor growth." (PMID 24722573, 2014). "Exposure of calreticulin has been observed in a variety of primary human cancer cells, in tumor cells subjected to mild disruption of calcium homeostasis, and in pre-apoptotic cancer cells undergoing ICD." (PMID 24480782, 2014). "In vitro and in vivo tumor irradiation induced significant upregulation of multiple components of the antigen-processing machinery and calreticulin cell-surface expression." (PMID 24480782, 2014). "For instance, the escape of calreticulin from the ER leads to the generation of an “eat-me” signal on the surface of tumor cells." (PMID 25386408, 2014). "Mounting evidence suggests that calreticulin exposure in tumor cells can occur under multiple circumstances as a result of ER stress." (PMID 24480782, 2014). "The expression of CALR, annexin A2, and annexin A3 in the tumor tissues was higher than that in the normal tissues." (PMID 24884814, 2014). "For instance, high levels of calreticulin serve as an “eat-me” signal on the surface of tumor cells." (PMID 25386408, 2014). "In defense of the calreticulin role as a protective mechanism against cancer, none of these studies have investigated the intracellular distribution of calreticulin in the respective tumor scenario." (PMID 25386408, 2014). "The presence of calreticulin on the tumor-cell surface requires PERK-mediated phosphorylation of the translation initiation factor eIF2a." (PMID 24480782, 2014). "Our data suggest that the increased CTL lysis of tumor targets exposed to radiation is a result of the direct interaction of exposed calreticulin with CTLs, as the augmented CTL killing was abrogated in the presence of a calreticulin blocking peptide." (PMID 24480782, 2014). "This type of cell death is characterized by the extracellular release of ATP and HMGB1, by the surface translocation of calreticulin, and by the subsequent phagocytosis of tumor cells by dendritic cells (DCs)." (PMID 24225025, 2013). "Oxaliplatin increases the expression of calreticulin on tumor cells, enhancing phagocytosis, antigen presentation, and ultimately their removal." (PMID 23577028, 2013). "Lastly, downregulation of calreticulin (CALR) has been established in the PCa specimens, and overexpression of CALR suppresses tumor growth and metastasis." (PMID 23365759, 2013). "Apoptosis of cancer cells has been reported to induce adaptive anti-tumor immune response through expression of some molecules, such as surface calreticulin, Hsp70, Hsp90 and soluble HMGB1 (high-mobility group box 1 protein)." (PMID 23935988, 2013). "Recently, the repressive effect of CALR on tumor invasion, including that of the prostate, has become a popular field of research." (PMID 22293781, 2012).
tumor (continued). "Previous studies demonstrated the CALR and its protein fragment (aa 1-180) vasostatin are endothelial cell inhibitors of tumor growth." (PMID 22293781, 2012). "Chemotherapeutic agents such as doxorubicin and oxaliplatin can cause massive tumor cell death and tissue damages, releasing various danger signals, such as high-mobility group protein B1 (HMGB1), calreticulin (CRT), and adenosine triphosphate (ATP)." (PMID 22778760, 2012). "In both in vitro and in vivo experiments we demonstrate that tumor growth and invasive abilities are reduced, while apoptosis is induced, in Ad-CALR/MAGE-A3-transfected U87 cells." (PMID 22293781, 2012). "The immunogenic properties of purified tumor cell-derived calreticulin can be explained by co-purification with calreticulin of various tumor-derived peptides or proteins." (PMID 22848581, 2012). "The in vivo study demonstrated that the tumor formation rate, and the average tumor growth rate, of the Ad-CALR/MAGE-A3-transfected group was significantly lower than that of the non-transfected, Ad-vector-transfected and Ad-CALR-transfected groups." (PMID 22293781, 2012). "Previous studies have also shown that calreticulin purified from tumor cells can elicit tumor-specific protective immunity." (PMID 22848581, 2012). "The mean tumor volume of the Ad-CALR/MAGE-A3 group from day 25 to the end was significantly smaller than that of the other groups, whereas there was no statistical differences among the other groups throughout the experimental period." (PMID 22293781, 2012). "Pioneering work by Zitvogel and colleagues has shown that the cytotoxic agents oxaliplatin and doxorubicin induce immunogenic cell death, as upon treatment with these agents, tumour cells transport calreticulin to their cell surface." (PMID 20924373, 2010). "The exposure of calreticulin provides a signal that is recognised by dendritic cells (DCs) and ultimately results in phagocytosis of the tumour cells." (PMID 20924373, 2010). "As known, Dox provides the exposure of the cell surface endoplasmic protein calreticulin that acts as an "eat me" signal and mediates the phagocytosis of tumor cells by DCs." (PMID 21040569, 2010). "The translocation of calreticulin and the subsequent tumor cells uptake by immature DCs are the first steps along a doxorubicin-induced DCs stimulatory pathway." (PMID 19925669, 2009). "The rate of tumour cells phagocytosis was positively correlated with the levels of exposed calreticulin in that it was increased by doxorubicin in HT29 cells, but not in HT29-dx and HT29 iNOS-cells." (PMID 19925669, 2009). "Calreticulin has been shown to be translocated on plasma membrane by anthracyclines and to trigger tumour cells uptake by iDC." (PMID 19925669, 2009). "Some types of chemotherapeutic drugs such as anthracyclins, as well as UV-C irradiation, can lead to the cell surface expression of calreticulin (CRT) which has recently been shown to confer anti-tumor immunogenicity to otherwise less immunogenic tumor cells." (PMID 18439316, 2008). "ACADS plays an essential role in activating ICD by upregulating CALR in tumour cells." (PMID 39800718, 2025). "High expression of calreticulin promotes intra-tumor infiltration of DC and CD4+ Th1 cells." (PMID 40356601, 2025). "Furthermore, the recruitment and maturation of immature dendritic cells (DCs) are induced, while the calreticulin ecto-CRT provides phagocytic signals to promote DC phagocytosis of tumor antigens." (PMID 40612869, 2025). "Interestingly, anti-GD2 not only inhibits anti-phagocytosis signals but also promotes “eat me” signals by upregulating surface calreticulin on tumor cells." (PMID 40835598, 2025). "First, OVs selectively infect and lyse tumor cells, inducing immunogenic cell death (ICD) and releasing damage-associated molecular patterns (DAMPs), including ATP, HMGB1, and calreticulin, alongside tumor-associated antigens (TAAs), thereby mediating direct tumor cytotoxicity." (PMID 41451200, 2025).